HOTAIRM1 (HOXA transcript antisense RNA, myeloid-specific 1)
Diseases named in the same sentence as HOTAIRM1 in open-access papers (continued):
Sharing a sentence is not in itself a finding about the gene and the disease.
glioblastoma (continued). "Since the majority of glioblastomas display copy number gains of chromosome 7, often due to trisomy 7, we evaluated the expression level of HOTAIRM1 in relation to chromosome 7 copy number status in glioblastomas." (PMID 34584066, 2021). "Glioblastoma patients whose tumors carried an IDH1 mutation, MGMT promoter methylation and low HOTAIRM1 expression showed the longest overall survival." (PMID 34584066, 2021). "Reduced TGM2 mRNA and protein levels in HOTAIRM1 stable knock-down LN-229, as well as other glioblastoma cell lines (U87MG, LN-18, and SF126) relative to control-transfected cells, were confirmed by RT-qPCR and Western blotting." (PMID 34584066, 2021). "In summary, we confirm and extend recent data implicating HOTAIRM1 as an oncogenic lncRNA driving tumor growth, therapy resistance, and poor prognosis of glioblastoma." (PMID 34584066, 2021). "Our data shows that HOTAIRM1 promotes TGM2 expression in glioblastoma cells, which is related to miRNA-mediated mechanisms implicating hsa-miR-17-5p." (PMID 34584066, 2021). "Since radiation sensitivity has been associated with intracellular ROS levels and since radiotherapy is an essential part of glioblastoma treatment, we investigated whether altered levels of HOTAIRM1 affect radiosensitivity of glioblastoma cells." (PMID 34584066, 2021). "In this way, H3K4me3‐activated HOTAIRM1 could contribute to glioblastoma development by enhancing the expression of neighboring HOXA1, an oncogene present in several cancers." (PMID 34316694, 2021). "Finally, the role of HOTAIRM1 in glioblastoma biology and radiotherapy resistance was characterized in vitro and in vivo." (PMID 34584066, 2021). "Moreover, our data suggest a novel role for HOTAIRM1 in regulating mitochondrial function and ROS levels in glioblastoma cells by modulating expression of TGM2, potentially by functioning as a miRNA sponge." (PMID 34584066, 2021). "Not only did we validate this finding in vitro, but our data indicate that high expression of HOTAIRM1 supports radioresistance of glioblastoma cells, which in turn may contribute to shorter patient survival as seen in our in vivo model." (PMID 34584066, 2021). "HOTAIRM1 is up-regulated in glioblastoma and promotes tumor cell migration and invasion." (PMID 34123828, 2021). "Therefore, the oncogenic HOTAIRM1/HOXA1 axis in glioblastoma may offer promise as a novel therapeutic target." (PMID 39015773, 2024). "Hence, targeting HOTAIRM1 may represent a promising therapeutic approach in glioblastoma, as it may function as an oncogene." (PMID 39015773, 2024). "Moreover, HOTAIRM1 modulates radiosensitivity of glioblastoma cells both in vitro and in vivo." (PMID 34584066, 2021). "Thus, in addition to the epigenetic modulation of HOXA1 and the sponging hsa-miR-129-5p and hsa-miR-495-3p, sponging of hsa-miR-17-5p (and potentially other TGM2-binding miRNAs) by HOTAIRM1 may cause increased TGM2 mRNA and protein expression in glioblastoma." (PMID 34584066, 2021). "Furthermore, HOTAIRM1 has been associated with shorter survival in glioblastoma patients, independent of IDH mutation and O6-methylguanine-DNA-methyltransferase promoter methylation, indicating its role as a driver of biological aggressiveness, radioresistance, and poor outcomes in glioblastoma." (PMID 39015773, 2024). "In glioblastoma multiforme (GBM), the HOTAIRM1 lncRNA oncogene, which is transcribed from the antisense direction of the HomeoboxA1 (HOXA1) gene, binds and sequesters G9a away from the HOXA1 gene promoter." (PMID 35740522, 2022). "Over-expression of HOTAIRM1 up-regulates HOXA1, which then increases the invasiveness of glioblastoma." (PMID 35521558, 2022). "In glioblastoma (BGM), researcher confirmed the upregulation of HOTAIRM1, and further demonstrated that HOTAIRM1 acted as a facilitator of malignant-behavior in BGM, which was shown to accelerate the occurrence of migration and invasion." (PMID 35087800, 2021).
glioblastoma (continued). "Silencing HOTAIRM1 impairs the proliferation, apoptosis, self-renewal, and tumorigenesis of GSCs, suggesting its crucial role in GSC stemness, and thus glioblastoma progression." (PMID 39015773, 2024). "In addition, growing evidence indicates that lncRNAs have various roles in resistance to glioblastoma therapies (e.g., MALAT1, H19) and in glioblastoma progression (e.g., CRNDE, HOTAIRM1, ASLNC22381, ASLNC20819)." (PMID 32650527, 2020). "We found that low levels of hsa-miR-17-5p expression are associated with shorter survival of glioblastoma patients in the TCGA cohort and that expression of hsa-miR-17-5p is inversely correlated with TGM2 expression in this cohort set, however, not with HOTAIRM1 expression." (PMID 34584066, 2021). "LncRNA HOTAIRM1 (HOX antisense intergenic RNA myeloid 1), which is located between the HOXA1 and HOXA2 genes, could interact with DNMTs and other epigenetic factors to sequester them away from HOXA1 promoter in glioblastoma multiforme (GBM)." (PMID 36533073, 2022).
leukemia (19 papers, 2015 to 2025). A malignant (clonal) hematologic disorder, involving hematopoietic stem cells and characterized by the presence of primitive or atypical myeloid or lymphoid cells in the bone marrow and the blood. "In NPM1-mutated AML, Hox antisense intergenic RNA myeloid 1 (HOTAIRM1) was highly expressed and promoted leukemia cell autophagy by regulating early growth response 1 (EGR1) and unc-51-like autophagy activating kinase 3 (ULK3)." (PMID 39596291, 2024). "Our data herein demonstrated the high level of lncRNA HOTAIRM1 in NPM1-mutated leukemia cells and indicated that HOTAIRM1 was upregulated at least partially by mutant NPM1 via KLF5-dependent transcriptional regulation." (PMID 34615546, 2021). "To investigate the potential mechanisms by which HOTAIRM1 contributes to the malignant phenotypes of NPM1-mutated leukemia cells, we examined its subcellular localization." (PMID 34615546, 2021). "In 215 IR-AML patients, high HOTAIRM1 expression was independently associated with shorter overall survival (OR:2.04;P = 0.001), shorter leukemia-free survival (OR:2.56; P < 0.001) and a higher cumulative incidence of relapse (OR:1.67; P = 0.046)." (PMID 26436590, 2015). "In conclusion, our study found that long noncoding RNA HOTAIRM1 can resist GC-induced apoptosis, and elucidated the mechanism from the perspective of upstream and downstream regulation of HOTAIRM1, revealing an epigenetic cause of glucocorticoid resistance in leukemia." (PMID 34262023, 2021). "Next, we explored the biological effects of high HOTAIRM1 expression in NPM1-mutated leukemia." (PMID 34615546, 2021). "The latest study even reported that HOTAIRM1 promoted autophagy and proliferation both in vitro and in vivo in leukemia cells." (PMID 37171645, 2023). "In this study, we established an acquired GC-resistant leukemia cell model and found a long noncoding RNA, HOTAIRM1, was overexpressed in the resistant cells by transcriptional profiling, and was higher expressed in patients with poor prognosis." (PMID 34262023, 2021). "Collectively, our findings reveal the oncogenic role of HOTAIRM1 and provide novel insights for future treatment of this distinct leukemia subtype." (PMID 34615546, 2021). "After investigating the role of nuclear HOTAIRM1, we explored the function of cytoplasmic HOTAIRM1 in leukemia cells." (PMID 34615546, 2021). "HOTAIRM1 was discovered as a myeloid-specific long noncoding RNA in promyelocytic leukemia cell, which was upregulated during differentiation induced by all-trans-retinoic acid." (PMID 34262023, 2021). "Then, we checked the expression of HOTAIRM1 in nine leukemia cells including K562, U937, THP1, Jurkat, CEM-C1-15, CEM-C7-14, RS4;11, SKNO-1, and Kasumi-1." (PMID 34262023, 2021). "Wright’s staining of bone marrow smears showed that HOTAIRM1 knockdown significantly reduced the number of leukemia cells." (PMID 34615546, 2021). "IHC staining of tissues infiltrated by leukemia cells with anti-Ki-67 antibodies further implied that knockdown of HOTAIRM1 can inhibit leukemia cell proliferation." (PMID 34615546, 2021). "Previous studies have identified HOTAIRM1 as a key lncRNA biomarker in several solid tumors, as well as in leukemia, by acting as tumor suppressors or oncogenes." (PMID 32284737, 2020). "By semi-qRT-PCR, we analysed HOTAIRM1 variants both in differentiating iPS and SH-SY5Y cells and, as control, in NB4 promyelocytic leukaemia cells induced to myeloid differentiation." (PMID 32661334, 2020). "As a potential lncRNA biomarker in leukemia, HOTAIRM1 was identified to activate the temporal collinear HOXA gene, including HOXA5." (PMID 31168296, 2019). "Among these lncRNAs, HOXB-AS3 is particularly interesting, because of the crucial roles of HOX genes in cell proliferation, hematopoiesis and leukemogenesis and the clinical significance of an anti-sense lncRNA in the HOX clusters, i.e., HOTAIRM1, in leukemia." (PMID 31234830, 2019).
leukemia (continued). "Long intergenic non-coding RNA HOTAIRM1 regulates cell cycle progression during myeloid maturation in leukemia cells." (PMID 28881797, 2017). "Similarly, high HOTAIRM1 expression has been linked to intermediate-risk AML and correlated with reduced overall and leukemia-free survival, as well as increased relapse risk." (PMID 40746924, 2025). "Both HOTTIP and HOTAIRM1, for example, have known roles in leukemia." (PMID 36139405, 2022). "Therefore, a deeper exploration of the biological significance of HOTAIRM1 in leukemia is imperative." (PMID 34615546, 2021). "Here, the cellular localization of HOTAIRM1 in leukemia cell lines remained the same regardless of the mutational status of NPM1." (PMID 34615546, 2021). "We first tested the role of nuclear HOTAIRM1 in leukemia cells." (PMID 34615546, 2021). "Our study indicates that HOTAIRM1 may be a promising therapeutic target for this distinct leukemia subtype." (PMID 34615546, 2021). "In leukemia, HOTAIRM1 was considered to be unfavorable and it could activate RHOA/ROCK1 pathway to enhance glucocorticoid resistance by inhibiting ARHGAP18." (PMID 35087800, 2021). "Indeed, the putative functional cooperation of the two ncRNAs, miR-196b and HOTAIRM1, in normal hematopoiesis and leukemia merits further investigation." (PMID 26436590, 2015). "Furthermore, to determine whether HOTAIRM1 regulates leukemia cell autophagy and proliferation via EGR1, we performed rescue experiments." (PMID 34615546, 2021). "Importantly, HOTAIRM1 promoted leukemia cell autophagy and proliferation in vitro and in vivo." (PMID 34615546, 2021). "Prompted by these findings, we further investigated the role of the downstream HOTAIRM1 target genes EGR1 and ULK3 in leukemia cells." (PMID 34615546, 2021). "Evidence shows that HOTAIRM1 is a critical regulator for the expression level of HOXA1 and HOXA4, which is involved in cell growth in leukemia cells." (PMID 30728826, 2018). "Furthermore, nuclear HOTAIRM1 promoted EGR1 ubiquitination by enhancing the MDM2-EGR1 interaction, while cytoplasmic HOTAIRM1 increased ULK3 expression by competitively sponging miR-152-3p, therefore contributing to leukemia cell autophagy and proliferation." (PMID 34615546, 2021). "Further study determined that HOTAIRM1 bound to the transcriptional inhibitory region of ARHGAP18 and repressed the expression of ARHGAP18, which led to the increase of RHOA/ROCK1 signaling pathway and promoted GC resistance through antiapoptosis of leukemia cells." (PMID 34262023, 2021). "However, a review of the literatures relative to HOTAIRM1 showed that HOTAIRM1 was previously explored only in thyroid, ovarian cancer, non-small cell lung cancer, leukemia, and clear cell renal cell carcinoma." (PMID 35087800, 2021).
Sepsis (15 papers, 2017 to 2025). Sepsis is defined as life-threatening organ dysfunction caused by a dysregulated host response to infection. "Since genetic targeting of S100A9 in mice limits MDSC expansion and sepsis-associated immunosuppression, molecular targeting of Hotairm1 is a plausible drug target for reversing sepsis-induced chronic immunosuppression." (PMID 33335790, 2020). "In addition, the amount of Hotairm1 transcripts associated with the unphosphorylated S100A9 protein significantly decreased following Hotairm1 knockdown in late sepsis MDSCs." (PMID 39665047, 2023). "By targeting HOXA1, HOTAIRM1 blockade alleviates lung injury and improves the survival of mice in an in vivo model of sepsis." (PMID 39713961, 2025). "Levels of noncoding RNA Hotairm1 are increasedsignificantly in MDSCs in mice and humans during late sepsis." (PMID 40458301, 2025). "This in vivo targeting ofHotairm1 significantly reduced IL-10 and TGF-βproduction by MDSCs, further supporting that Hotairm1 couples withS100A9 to promote sepsis-induced immunosuppression byincreasing IL-10 and TGF-β levels during late sepsis." (PMID 40458301, 2025). "A prominent example of the role of non-coding RNAs in immune reprogramming is the long non-coding RNA (lncRNA) HOTAIRM1, which has been shown to promote T-cell exhaustion during sepsis." (PMID 39594987, 2024). "Levels of Hotairm1 transcripts significantly increase in MDSCs in septic patients who develop late/protracted sepsis state, concurrent with an accumulation of unphosphorylated S100A9 protein in the nucleus." (PMID 39665047, 2023). "Knockdown of Hotairm1 in MDSCs from mice and humans with late sepsis increases phospho-S100A9 protein." (PMID 39665047, 2023). "We reported that chemical inhibition of KDM6A by GSK-J4 significantly reduces Hotairm1 transcripts in late sepsis Gr1+CD11b+ cells." (PMID 39665047, 2023). "This leads to the conclusion that the Notch/Hes1/HOTAIRM1/HOXA1/PD-L1 axis is critical for sepsis-induced immunosuppression." (PMID 36834869, 2023). "Hotairm1 transcription in Gr1+CD11b+ cells during sepsis is regulated by an epigenetic mechanism that involves histone methylation and binding of transcription factor PU.1 at its proximal promoter." (PMID 39665047, 2023). "We found that levels of Hotairm1 transcripts are elevated in MDSCs from mice and humans with late sepsis, concurrent with the accumulation of S100A9 protein in the nucleus." (PMID 39665047, 2023). "Hotairm1 transcripts are detected at low levels in early sepsis Gr1+CD11b+ cells and are significantly increased in late sepsis." (PMID 39665047, 2023). "Conversely, the knockdown of Hotairm1 in late sepsis Gr1+CD11b+ MDSCs increased S100A9 protein phosphorylation." (PMID 39665047, 2023). "We have previously reported that the increase in Hotairm1 transcripts in MDSCs during late sepsis emerges from epigenetic modifications at its proximal promoter." (PMID 39665047, 2023). "We found that depletion of Hotairm1 from late sepsis MDSCs from mice and humans restores levels of phospho-S100A9 protein." (PMID 39665047, 2023). "Western blot analysis of the bead-bound RNA-protein complexes showed increased S100A9 protein binding to Hotairm1 in late sepsis Gr1+CD11b+ cells." (PMID 39665047, 2023). "Hotairm1 RNA is detected in Gr1+CD11b+ cells at low levels during early sepsis, but it increases significantly during late sepsis, concurrently with the accumulation of unphosphorylated S100A9 protein in the nuclear compartment." (PMID 39665047, 2023). "Inhibiting KDM6A demethylase activity with its specific inhibitor GSK-J4 in late sepsis Gr1+CD11b+ cells significantly reduces Hotairm1 levels." (PMID 39665047, 2023). "Our findings that Hotairm1 knockdown in late sepsis MDSCs from mice and humans increased S100A9 phosphorylation and reduced IL-10 production are biologically significant." (PMID 39665047, 2023).
Sepsis (continued). "In early sepsis, the Hotairm1 promoter is enriched with the transcriptionally repressive histone mark H3K27me3, which inhibits its promoter transcription by PU." (PMID 39665047, 2023). "Increasing Hotairm1 transcripts in early sepsis Gr1+CD11b+ cells diminished S100A9 phosphorylation by p38 MAPK." (PMID 39665047, 2023). "In early sepsis Gr1+CD11b+ cells, the Hotairm1 promoter is enriched with the repressive transcription histone mark H3K27me3, which inhibits its promoter transcription." (PMID 39665047, 2023). "In a sepsis mouse model, the lncRNA HOTAIRM1 (HOXA transcript antisense RNA myeloid-specific 1) is highly expressed in the late phase of the disease." (PMID 36834869, 2023). "Conversely, increasing Hotairm1 in early sepsis Gr1+CD11b+ cells by transfection decreases phospho-S100A9 protein levels." (PMID 39665047, 2023). "Histone demethylase KDM6A inhibits H3K27 trimethylation that is necessary for PU.1 binding at Hotairm1, and induces Hotairm1 transcription activation in MDSCs during sepsis." (PMID 36439186, 2022). "Here, we found that KDM6A specific inhibitor GSK-J4 supports an exchange between H3K27me3 and H3K4me3 at Hotairm1 promoter in mouse and human MDSCs, thereby mediating the effect of other bioactive mediators of sepsis immunosuppression (e.g., IL-10)." (PMID 35185915, 2022). "Here, we used KDM6A potent and specific inhibitor GSK-J4 to modulate Hotairm1 RNA transcription in sepsis MDSCs." (PMID 35185915, 2022). "ChIP analysis of Hotairm1 promoter showed that KDM6A binding was significantly higher in MDSCs from mice with later sepsis compared with early sepsis." (PMID 35185915, 2022). "In this study, we extended our mechanistic and translational research by identifying KDM6A as a promoter of the epigenetic exchanges that induce Hotairm1 transcription in MDSCs during sepsis." (PMID 35185915, 2022). "KDM6A binding to the Hotairm1 promoter in MDSCs from mice with later sepsis correlates with Hotairm1 transcription activation." (PMID 35185915, 2022). "We also reported that levels of lncRNA Hotairm1 in MDSCs increase in mice with later/protracted sepsis." (PMID 35185915, 2022). "The immunosuppressive IL-10 cytokine, whose levels increase significantly during later sepsis, promotes the Hotairm1-mediated shuttling of S100A9 protein to the nucleus in MDSCs." (PMID 35185915, 2022). "Hotairm1 shuttles S100A9 protein to the nucleus in myeloid precursors to program them into MDSCs during later sepsis." (PMID 35185915, 2022). "Because Hotairm1 couples with S100A9 to program MDSCs during later sepsis, our findings underscore the importance of removing H3K4me3 in limiting excessive MDSC accumulation during later sepsis in humans." (PMID 35185915, 2022). "We reported that sepsis MDSC development requires long non-coding RNA Hotairm1 interactions with S100A9." (PMID 35185915, 2022). "Although both Ezh2 and KDM6A protein expression in MDSCs remains unchanged during sepsis, KDM6A binding at Hotairm1 promoter increases significantly after sepsis induction." (PMID 35185915, 2022). "The lncRNA, HOXA transcript antisense RNA myeloid-specific 1 (Hotairm1), promotes myeloid precursor to differentiate to MDSCs in sepsis." (PMID 36439186, 2022). "We conclude that KDM6A plays an important role in reducing repressor mediator H3K27me3 on the Hotairm1 promoter, thereby increasing Hotairm1 during sepsis." (PMID 35185915, 2022). "Our previous studies showed that Hotairm1 modifies the S100A9 protein’s function to generate MDSCs during later sepsis." (PMID 35185915, 2022). "To support translation to human sepsis, we demonstrate that inhibiting H3K27me3 demethylation by KDM6A ex vivo in MDSCs from patients with protracted sepsis decreases Hotairm1 transcription." (PMID 35185915, 2022). "KDM6A protein binds to Hotairm1 proximal promoter following sepsis initiation, and its binding peaks in later sepsis MDSCs." (PMID 35185915, 2022).